BCL9 (BCL9 transcription coactivator)
Description:
Involved in signal transduction through the Wnt pathway. Promotes beta-catenin's transcriptional activity (By similarity).
Synonyms: LGS
Tractability: Small molecule: a structure with a bound ligand is known; a high-quality ligand is known. PROTAC: its protein half-life has been measured; a small molecule that binds it is known.
Gene: Protein-coding gene on chromosome 1 (147,541,501 to 147,626,216, forward strand). Ensembl gene ENSG00000116128.
Subcellular location: Nucleus
Subcellular location (Human Protein Atlas): Nuclear bodies; Nucleoplasm; Cytosol
Pathways (Reactome):
Signal Transduction: Deactivation of the beta-catenin transactivating complex; Formation of the beta-catenin:TCF transactivating complex
Gene Ontology:
Molecular function: protein binding; beta-catenin binding; transcription coactivator activity
Biological process: regulation of transforming growth factor beta receptor signaling pathway; canonical Wnt signaling pathway; positive regulation of transcription by RNA polymerase II
Cellular component: beta-catenin-TCF complex; cis-Golgi network; nucleoplasm; cytoplasm; Golgi apparatus; nucleus
Genetic constraint (gnomAD): Loss-of-function variants: 25 observed, 93.3 expected, observed/expected ratio (o/e) 0.27, 90% interval 0.19 to 0.37. The upper end of that interval is the gene's LOEUF score, 0.37, which puts it in group 1 of 6, group 1 being the genes least tolerant of losing a copy. Missense variants: 1,817 observed, 1,976.7 expected, observed/expected ratio (o/e) 0.92, 90% interval 0.88 to 0.95. Synonymous variants: 711 observed, 709.13 expected, observed/expected ratio (o/e) 1, 90% interval 0.94 to 1.07.
Gene-disease validity (ClinGen):
ClinGen rates the evidence that BCL9 causes each of these diseases.
congenital heart disease (autosomal dominant): Limited. A heart disease that is present at birth.
Cancer hallmarks: angiogenesis (promotes); proliferative signalling (promotes); invasion and metastasis (promotes)
Homologues: Orthologues: chimpanzee BCL9 (99% identical), macaque BCL9 (99% identical), rabbit BCL9 (97% identical), dog BCL9 (96% identical), guinea pig BCL9 (96% identical), rat Bcl9 (95% identical), mouse Bcl9 (95% identical), pig BCL9 (92% identical), tropical clawed frog bcl9 (74% identical), zebrafish bcl9 (60% identical). Paralogues in human: BCL9L (35% identical).
Diseases named in the same sentence as BCL9 in open-access papers:
BCL9 is named in the same sentence as 88 diseases in open-access papers, as found by Europe PMC text mining. Sharing a sentence is not in itself a finding about the gene and the disease. The quoted sentences say what the papers report.
colorectal cancer (26 papers, 2008 to 2025). A primary or metastatic malignant neoplasm that affects the colon or rectum. "Current studies have observed the association between the overexpression of BCL9 and tumor formation, including breast cancer, renal cell carcinoma, hepatocellular carcinoma, and colorectal cancer." (PMID 38269250, 2023). "Importantly, the gene signature of Bcl9/Bcl9L knockout cells is negatively associated with the high stemness subtypes of colorectal cancers and positively correlates with patient overall survival." (PMID 34545187, 2021). "However, the exact molecular mechanism for the regulation of the Pygo and Bcl9 co-factors and their role in Apc- or Ctnnb1-associated colorectal cancer requires further analyses." (PMID 27811361, 2016). "The favorable safety profile provides a strong foundation for the further development of Bcl9@TP as a clinically relevant nanoplatform for colorectal cancer treatment." (PMID 40948801, 2025). "Targeting the CD155-CD226 axis has emerged as a promising strategy for enhancing the response to anti-PD-1 therapy, as Bcl9-depleted or -inhibited colorectal cancer cells exhibit improved therapeutic sensitivity." (PMID 40362354, 2025). "Earlier research has revealed the potential functions of BCL9 in tumor metastasis and invasion in colorectal cancer and significant upregulation was observed in ACC." (PMID 38269250, 2023). "Recent studies showed that the deletion of BCL9 and BCL9l in colorectal cancer was found to inhibit colon tumorigenesis driven by an abnormal Wnt signaling pathway." (PMID 36835467, 2023). "Recently, β-catenin-independent BCL9 functions have also emerged through interactions with paraspeckle proteins in colorectal cancer, indicating BCL9 oncogenic functions expand beyond the Wnt cascade." (PMID 35204808, 2022). "For example, knockout of Bcl9/Bcl9L in a mouse model of colorectal cancer has resulted in the reprogramming of cancer cells from a stemness state to differentiation manifested by the downregulation of EMT-related gene expression." (PMID 34545187, 2021). "Here we find that, in colorectal cancer cells and in developing mouse forelimbs, BCL9 proteins sustain the action of β-catenin in a largely PYGO-independent manner." (PMID 32808927, 2020). "BCL9 has also been identified as an oncogene in multiple myeloma where BCL9 is upregulated, and disrupting the β-catenin–BCL9 interaction has been shown to decrease transcription of Wnt target genes in colorectal cancer." (PMID 32759724, 2020). "BCL9 and B9L are often overexpressed in colorectal cancer cell lines and carcinomas, maintaining their β-catenin-dependent transcription, and overexpressed B9L promotes intestinal tumourigenesis." (PMID 30760710, 2019). "Our results demonstrate a key role of the Wnt enhanceosome in β-catenin-dependent intestinal tumourigenesis and reveal the potential of BCL9 as a therapeutic target during early stages of colorectal cancer." (PMID 30760710, 2019). "Here, the authors show that deletion of Bcl9 and Pygo suppresses tumorigenesis and extends disease free survival in two different colorectal cancer models, suggesting a strategy for drugging β-catenin signalling in this cancer." (PMID 30760710, 2019). "Our results from this model therefore illustrate the significant potential of BCL9 and Pygo as targets for therapeutic interference in colorectal cancer." (PMID 30760710, 2019). "The Apc1332T model has allowed us to discover a crucial role of Bcl9 and Pygo in effecting intestinal neoplasia in a model with high relevance for colorectal cancer." (PMID 30760710, 2019). "B-cell CLL/lymphoma 9 protein (BCL-9), a multi-functional co-factor in Wnt signaling, induced carcinogenesis as well as promoting tumor progression, metastasis and chemo-resistance in colorectal cancer (CRC)." (PMID 27121066, 2017).
colorectal cancer (continued). "We have shown that a high percentage of human colorectal cancer specimens display elevated BCL-9 expression levels, but the underlying mechanism for the increased expression of BCL-9 in CRC is unclear." (PMID 27121066, 2017). "BCL9 is frequently overexpressed in a variety of solid tumors including colorectal cancer, multiple myeloma and HCC." (PMID 28074862, 2017). "We have used overexpression of dominant-negative forms of BCL9, and RNAi-mediated depletion, to study its function in human cell lines with elevated Wnt pathway activity, including colorectal cancer cells." (PMID 18627596, 2008). "Thirdly, both BCL9 and B9L are Wnt-inducible genes that are hyperexpressed in colorectal cancer cell lines, indicating that they are part of a positive feedback loop, reinforcing Wnt pathway activity." (PMID 18627596, 2008). "We found that BCL9 is required for efficient β-catenin-mediated transcription in Wnt-stimulated HEK 293 cells, and in the SW480 colorectal cancer cell line whose Wnt pathway is active due to APC mutation." (PMID 18627596, 2008). "The functional importance and hyperexpression of BCL9 in colorectal cancer cells indicates the potential of this protein as a cancer drug target." (PMID 18627596, 2008). "In the course of our analysis, we discovered that BCL9 and B9L are both Wnt-inducible genes, and that they are hyperexpressed in colorectal cancer cells whose Wnt pathway is constitutively active." (PMID 18627596, 2008). "Our evidence for the requirement of BCL9 in the TCF-dependent transcription of colorectal cancer cells, and its hyperexpression in these cells, has revealed its potential as a target for inhibitory drugs." (PMID 18627596, 2008). "BCL9 functions in cell-cell communication in colorectal cancer." (PMID 38466776, 2024). "Yet, other transcription factors may also interact with Bcl9/Bcl9L and β-catenin to modulate their transcriptional output, as for example shown for the Tbx3-mediated promotion of colorectal cancer cell metastasis." (PMID 34545187, 2021). "Suppression of Bcl9 inhibits tumor growth in mouse models of colorectal cancer (CRC)." (PMID 34566638, 2021). "Here, the authors show a β-catenin independent function of BCL9 in a subtype of colorectal cancers, where it interacts with paraspeckle proteins to enhance the mRNA stability of calcium signalling and neural associated genes to promote communication with tumour cells and its microenvironment." (PMID 31911584, 2020). "Thus, BCL9 and B9L have significant potential as targets for therapeutic intervention in colorectal cancer." (PMID 30760710, 2019). "Thus, B9L and to some extent BCL9 are hyperexpressed in colorectal cancer cells compared to unstimulated HEK 293 cells – in the case of B9L, more than an order of magnitude, much like some of the other TCF target genes." (PMID 18627596, 2008). "BCL9 is required for efficient β-catenin-mediated transcription in human cell lines whose Wnt pathway is active, including colorectal cancer cells, indicating its potential as a drug target in colorectal cancer." (PMID 18627596, 2008). "Finally, we show that BCL9 and B9L are both Wnt-inducible genes, hyperexpressed in colorectal cancer cell lines, indicating that they are part of a positive feedback loop." (PMID 18627596, 2008). "To see whether the L>F and L>K mutations affected the subcellular distributions of BCL9 or BCL9-2, we expressed these proteins in SW480 colorectal cancer cells whose Wnt pathway activity is high, due to mutation of APC." (PMID 18627596, 2008). "Notably, Bcl9@TP markedly potentiated the therapeutic efficacy of ICIs, highlighting its promise as a combinatorial strategy to overcome immune resistance and enhance antitumor immunity in colorectal cancer." (PMID 40948801, 2025).
colorectal cancer (continued). "B9L expression was also reduced after BCL9 depletion (which thus mimics a double knock-down of both paralogs, albeit a partial one) although the converse was not true, possibly because this gene is only mildly Wnt-inducible, and is less hyperactive than B9L in colorectal cancer cell lines." (PMID 18627596, 2008). "However, further validation of BCL9 proteins as drug targets in colorectal cancer will be required, including the analysis of their function in Wnt signaling during mammalian development and in adult tissue homeostasis, and of their role in promoting intestinal tumorigenesis in animal models." (PMID 18627596, 2008). "BCL9 has an oncogenic function as it is overexpressed in many solid tumors including HCC and colorectal cancer; this is combined with a poor prognosis of HCC cases." (PMID 34978646, 2022). "Firstly, BCL9 is required for efficient TCF-mediated transcription in Wnt-stimulated and colorectal cancer cells." (PMID 18627596, 2008). "BCL9 is absent in normal cells and frequently over-expressed in a variety of solid tumors including colorectal cancers, multiple myeloma and HCC12." (PMID 28074862, 2017). "Given the Wnt-responsiveness of BCL9 and B9L in HEK 293 cells, we wondered whether these genes might be hyperexpressed in colorectal cancer cell lines." (PMID 18627596, 2008). "Neither mammalian Pygo nor BCL9 is required for Wnt-mediated ISC proliferation or maintenance during homeostasis, but both promote Wnt target gene expression in colorectal cancer." (PMID 28708826, 2017).
colon carcinoma (23 papers, 2006 to 2025). "This reduced rate of colonic tumour formation translated into a survival benefit with Bcl9/9l deficiency." (PMID 30760720, 2019). "A key observation from the tumour models driven by APC loss was that deletion of Bcl9/9l favoured adenoma formation within the proximal SI, whilst colonic tumour growth was suppressed." (PMID 30760720, 2019). "High BCL9 expression was associated with a poor prognosis in colon cancer patients." (PMID 31827404, 2019). "For instance, deletion of Bcl9 and Bcl9l or Pygo1 and Pygo2 significantly extended survival in both ApcMin/+ and Apc1322T/+ mouse models of colon cancer." (PMID 37048063, 2023). "Our finding of negative regulation of Per1 in TIME of colon tumor provided evidence for BCL9-driven Wnt signaling role in circadian disruption." (PMID 34566638, 2021). "We grouped single cells of mouse colon cancer cells treated with BCL9 KD and BCL9 inhibitors according to the similarity of their mRNA expression, and found that the two groups 7 and 8 have markers related to endothelial cells and fibroblasts." (PMID 33552975, 2020). "The colonic tumours that formed in VillinCreERApcfl/flBcl9fl/flBcl9lfl/fl mice retained expression of both Bcl9 and Bcl9l, suggesting that BCL9/9l are required for colonic tumour growth following the loss of APC." (PMID 30760720, 2019). "To determine a role for BCL9/9l in colonic tumour growth we injected 4-hydroxy tamoxifen into the colonic submucosa of VillinCreERApcfl/fl and VillinCreERApcfl/flBcl9fl/flBcl9lfl/fl mice to induce local recombination." (PMID 30760720, 2019). "BCL9 has been described as a promoter of tumor progression and invasion in different tumor entities, such as colon carcinoma and multiple myeloma." (PMID 30197759, 2018). "BCL9 was reported to be an important factor in determining the proliferation, migration, invasion and the metastatic potential of multiple myeloma and colon carcinoma cells." (PMID 28074862, 2017). "Previous studies in colon carcinoma and multiple myeloma models showed that tumors with BCL9 KD exhibited altered expression and distribution of mesenchymal and epithelial markers, vimentin, β-catenin and E-cadherin, indicative of reduced EMT." (PMID 26384318, 2015). "The main conclusion from this study is that fusion of E1A to the BCL9 HD2 domain increases the activity of Tcf-regulated oncolytic adenoviruses in most colon cancer cell lines in vitro." (PMID 17020613, 2006). "In addition to its role in shaping the tumor immune microenvironment—particularly by promoting CD8+ T-cell and dendritic cell infiltration—BCL9 has also been shown to influence endothelial cell fate in a mouse model of colon cancer." (PMID 40362354, 2025). "We wondered whether oncogenic BCL9 highly expressed in colon cancer correlates with antigen presentation." (PMID 38811552, 2024). "Interestingly, BCL9 acts as an enhancer of β-catenin signaling in colon cancer and is considered to be an oncogene, and the WT form of BCL9 seems to slightly suppress the canonical pathway." (PMID 36612190, 2022). "In colon carcinoma, Wnt responsiveness of BCL9 and BCL9L themselves has been proposed." (PMID 31440992, 2020). "Similarly, RNAi-mediated knockdown of the BCL9L homologue BCL9 in colon cancer and multiple myeloma cell lines led to inhibition of cell proliferation, migration and invasion." (PMID 27713160, 2016). "BCL9 has been shown to promote progression of multiple myeloma and colon carcinoma." (PMID 26384318, 2015). "Furthermore BCL9 knock-down tumors show a less aggressive phenotype and result in increased host survival in mouse xenograft models of multiple myeloma and colon carcinoma." (PMID 23825644, 2013). "In summary, hsBCL9z96 demonstrates robust antitumor activity in colon cancer, melanoma and breast cancer models with improved feature of cell permeability, suggesting hsBCL9z96 is a good research tool of pharmacological inhibition of BCL9/β-catenin driven Wnt transcriptional activity." (PMID 38811552, 2024).
colon carcinoma (continued). "In an analysis of a GEO dataset, expression levels of EpCAM, BCL9, and DVL1 were increased in colon cancer liver metastasis compared with primary tumors." (PMID 34790117, 2021). "Oncogenic function of the homologs BCL9 and BCL9L is well characterized in colon cancer, where BCL9 proteins are frequently overexpressed." (PMID 31440992, 2020). "In order to answer these questions, we use RNAi genetic deprivation or small molecule inhibitors to influence the BCL9 and the Wnt signaling pathway in the CT26 colon cancer mice model." (PMID 33552975, 2020). "Unexpectedly, we found that deletion of Bcl9/9l accelerated an APC-driven model of intestinal tumorigenesis and favoured adenoma formation within the proximal SI, but suppressed colonic tumour growth." (PMID 30760720, 2019). "Here deletion of Bcl9/9l reduces intratumoural Wnt signalling, favouring tumour formation in the proximal SI, but is not permissive for colonic tumour formation due to the relatively low underlying basal Wnt signalling; observations which support the ‘just-right’ Wnt signalling hypothesis." (PMID 30760720, 2019). "Deletion of Bcl9 and Bcl9l reduces colonic regeneration following acute colitis and decreases expression of Wnt target genes and ISC markers in colonic tumours generated by chemical carcinogenesis." (PMID 30760720, 2019). "There are several interesting genes within the amplicons, including BCL9 (B-cell CLL/lymphoma 9), which has recently been characterised as an oncogene in colon carcinoma and multiple myeloma, with a role in the Wnt pathway." (PMID 20844748, 2010). "To validate whether a correlation of EpCAM and BCL9/CTNNB1 exists in cancers, we analyzed the correlations of EpCAM and BCL9 as well as EpCAM and CTNNB1 in lung cancer, colon cancer, esophageal cancer, stomach cancer, head and neck cancer, and kidney cancer." (PMID 34790117, 2021). "By genetic depletion and pharmacological inhibition of BCL9 in tumors, we found that BCL9 suppression reduced tumor growth, promoted CD8+ T cell tumor infiltration, and enhanced response to anti-PD-1 treatment in mouse colon cancer models." (PMID 34417435, 2021). "The results suggested that BCL9 does not affect the expression of β-catenin in either of the ovarian cancer cell lines, which is consistent with research on multiple myeloma and colon cancer cells." (PMID 31827404, 2019). "BCL9 promotes the proliferation, invasion, migration, angiogenesis, and epithelial–mesenchymal transition of colon cancer cells and multiple myeloma cells, but it does not affect β-catenin protein expression." (PMID 31827404, 2019). "Indeed, a BCL9 peptide mimetic was shown to disrupt native β-catenin/BCL9 complexes and lead to reduced WNT target gene expression in colon cancer cell lines and inhibited tumour growth in a colon cancer xenograft model Other small molecule inhibitors of BCL9 have also been discovered." (PMID 37048063, 2023). "The expression of BCL9 was NOT increased as we have previously reported in human colon cancers." (PMID 27811361, 2016).